AKT1 (AKT serine/threonine kinase 1)
Diseases named in the same sentence as AKT1 in open-access papers (continued):
Sharing a sentence is not in itself a finding about the gene and the disease.
cancer (continued). "Further studies shall reveal whether the expression of the Akt1-E17K mutation in human tumour cell lines or primary cancer cells from patient samples is associated with increased radioresistance." (PMID 28209968, 2017). "Therefore, a systematically meta-analysis was performed to evaluate the association between the five SNPs (mTOR rs2295080 and rs2536, AKT1 rs2494750 and rs2494752, pTEN rs701848) and cancer risk by systematic review of the literature in 31 eligible studies." (PMID 29259266, 2017). "To date, numerous studies have investigated the association of genetic polymorphisms of pTEN/AKT/mTOR pathway genes including rs2295080, rs2536 of mTOR gene, rs2494750 and rs2494752 in the AKT1 gene, pTEN rs701848 with cancer susceptibility, however, the results were inconclusive." (PMID 29259266, 2017). "Data from these studies will provide further insight into whether AZD5363 delivers clinical benefit to patients with advanced cancer in combination with chemo- or endocrine therapy, and as monotherapy in Akt1-mutation-selected patients." (PMID 26931343, 2016). "In our study, we obtained sequencing data on 50 cancer‐related genes in cases of pediatric AF and compared them with findings in the adult counterpart of AF, identifying significant differences mainly involving AKT1 and BRAF mutations in pediatric AF." (PMID 27062580, 2016). "In addition, AKT1 hotspot E17K mutations were found to be significantly more frequent in SF3B1 K700E mutated tumours (4/16) than in matched wild-type cancers (0/32, p = 0.009353, Fisher's exact test)." (PMID 25424858, 2015). "Since then, AKT1-E17K mutation has been identified at low frequency in multiple cancer types." (PMID 26053093, 2015). "Moreover, we re-sequenced five exons from three frequently-mutated cancer genes, AKT1, PIK3CA, and BRAF, in an additional 120 ESCC samples." (PMID 26386145, 2015). "One study also reported an association between the AKT1 polymorphism and cancer metastasis." (PMID 24632578, 2014). "Although AKT1 mutations are found in about 2% of all cancers, they mainly occur at amino acid 15 and the functional importance of mutation at other sites is unknown." (PMID 21781349, 2011). "Despite the confirmed oncogenic function of the AKT1 E17K, the rare incidences of the mutation suggest that it may not play a crucial role in the development of the most common types of human cancers." (PMID 18392055, 2008). "Notably, Akt1 activity is linked to aggressive features and metastatic potential in these cancers." (PMID 40798865, 2025). "However, it is Akt1 that has been most associated with cancer." (PMID 32211045, 2020). "Moreover, carrying AKT1 rs2494752 AG and GG/AG genotypes showed an increased overall cancer risk." (PMID 29259266, 2017). "Considering the role of AKT1 in facilitating cancer development and progression, the increased levels of AKT1 in the presence of the rs2494752 G variant allele in the promoter may increase cancer susceptibility, which may explain our findings of cancer risk associated with this SNP." (PMID 26818920, 2016).
cancer (continued). "However, the combined analysis of three AKT1SNPs identified that individuals carrying only one of three AKT1 variant genotypes might have decreased risk to develop ESCC cancer in comparison with non‐carriers, but this finding could be because of chance." (PMID 26828791, 2016). "Thus, there may be “race-specific” differences in the contribution of polymorphisms to AKT1 expression and, consequently, to cancer risk." (PMID 24632578, 2014). "AKT1 is a key oncogenic factor involved in the pathogenesis of various cancers, including lung, nasopharyngeal, breast, liver, and ovarian cancers." (PMID 41584043, 2026). "CK inhibits AKT1 activity, activates the expression of apoptotic proteases Caspase-3, Caspase-8, and Caspase-9, induces cancer cell apoptosis, and also inhibits cancer cell migration and invasion." (PMID 40422575, 2025). "Since both are directly linked to p21-activated kinase 1, which is heavily implicated in cancer, this also leads to potential regulation with GSK3 and Akt1 and ubiquitination-dependent degradation, again potentially providing upstream avenues for validation." (PMID 41294712, 2025). "AKT1, TSC1, and TSC2 (Tuberous Sclerosis Complex 1 and 2), which encode the proteins hamartin and tuberin, respectively, are crucial in PTEN-mediated cancer progression." (PMID 39891849, 2025). "AKT1, a serine/threonine kinase regulating cell growth and survival pathways, demonstrates frequent overexpression in cancers." (PMID 41312415, 2025). "Several studies have indicated that the Akt1 signaling pathway is aberrantly upregulated in tumors and plays a key role in cancer metastasis." (PMID 40082743, 2025). "Given that AKT1 hyperactivation is associated with poor prognosis in several cancers, this role of SETDB1 further underscores its importance in cancer progression." (PMID 39945463, 2025). "This binding behavior is biologically significant, as it reflects the ability of Nyctanthic acid to remain anchored at the active site—an essential trait for sustained inhibition of AKT1 signaling in cancer cells." (PMID 40933552, 2025). "During disease progression, these cells exhibited a shift toward hypermethylation and the epigenetic involvement of the PI3K/AKT and MAPK signaling pathways, with AKT1 phosphorylation emerging as a hallmark of cancer advancements." (PMID 40722776, 2025). "While the Q. infectoria compounds demonstrate promising interaction profiles against specific cancer‐related signaling proteins, the binding affinities of Nyctanthic acid against AKT1 and GAPDH reflect even more favorable energetics in our selected targets." (PMID 40933552, 2025). "AKT1 inhibitors, such as MK-2206 (in clinical trials for cancer), have been shown to play a significant role in suppressing osteoclast differentiation." (PMID 40313558, 2025). "In cervical cancer, members of the TGFβ superfamily promote cancer stem cell-like properties through the activation of the Akt1/Erk1/2/MZF1 signaling axis and upregulation of the stem cell marker CD73." (PMID 41373619, 2025). "AKT1 is typically activated in cancer through the activation of the PI3K pathway or through the inactivation of PTEN." (PMID 40896440, 2025). "It has also been demonstrated that the drug promotes apoptosis by reducing AKT1 activity, enhancing cancer cell sensitivity to TRAIL, increasing ROS levels, and disrupting mitochondrial membrane potential (MMP)." (PMID 40422575, 2025). "Specifically, nine depsidone compounds were subjected to in silico docking against key cancer-related protein targets, including AKT1, CDK2, ERK1, and TNFα." (PMID 40942174, 2025).
cancer (continued). "In this specific tumor analysis, the mTOR inhibitor class of agents (via targeting AKT1 overexpression) scored the highest when compared to normal references with a Z-score of 3.7 and scored in the 96 percentile when compared to Cancer Reference Control (CRC)." (PMID 41560724, 2025). "Molecular docking further substantiated their therapeutic relevance, showing high binding affinity to key cancer-related targets like AKT1, CDK2, ERK1, and TNFα." (PMID 40942174, 2025). "Pharmacological inhibition of AKT1 not only diminishes RUNX2 expression but also impairs the maintenance of cancer stem-like cell populations, indicating therapeutic sensitivity of this regulatory mechanism." (PMID 40862758, 2025). "Further, the top‐ranked flavonoid was assessed for its effect against the FOXO3 (an Akt1 downstream target) gene expression in Human MCF‐7 cancer cells." (PMID 40798865, 2025). "Molecular docking revealed strong binding affinities between these compounds and cancer-related targets (AKT1, CDK2, ERK1, TNFα), with simplicildone D and mollicellin G demonstrating particularly high interactions." (PMID 40942174, 2025). "In psoriatic tissue, qRT-PCR analysis found an overexpression of AKT1, positively regulated by BLACAT1 (the lncRNA bladder cancer-associated transcript 1), which also functioned as a competing endogenous RNA (ceRNA) in relation to miR-1495p." (PMID 40725772, 2025). "Targeting AKT1 or restoring FOXO function is considered a potential therapeutic strategy due to the significant function of the AKT1-FOXO relationship in cancer progression." (PMID 41011149, 2025). "Epistatic investigations show that ADAR1 mutations are mutually exclusive with genes such as PTEN, Akt1, and BLCAP, which appear to be required for cancer cell survival when ADAR1 is compromised." (PMID 40852728, 2025). "Among the significantly enriched pathways, the ‘PI3K-Akt signaling pathway’ is one of the most prominent and significant cancer-related pathways, with AKT1 serving as a central node in this pathway." (PMID 41220926, 2025). "AKT1 has a critical role in cancer metastasis and angiogenesis, AKT2 is involved in insulin metabolism, and AKT3 is mainly found in the brain cortex and hippocampus and is essential in regulating brain size." (PMID 39717717, 2025). "This highlights the promising therapeutic potential of specific flavonoids as Akt1 inhibitors and warrants further in vivo validation to confirm their efficacy in cancer treatment." (PMID 40798865, 2025). "Database synthesis corroborated disease associations involving MTOR and its partners (e.g., TSC2, RICTOR, RPTOR, MLST8, AKT1 across selected carcinomas)." (PMID 41300706, 2025). "In cancer cells, AKT1 is involved in cell proliferation and growth, thereby facilitating tumor development and suppressing apoptosis." (PMID 38255807, 2024). "Inhibiting AKT1 can suppress tumor growth, induce apoptosis, and enhance the efficacy of existing treatments by sensitizing cancer cells to chemotherapy and radiotherapy." (PMID 39275052, 2024). "In our cohort of patients with HR+/HER2- cancer, we found new AKT1 E17K alterations in 5% of patients in the BL cfDNA draw, 1% of patients in the 2nd draw, and 3% of patients in the 3rd draw." (PMID 38605020, 2024). "In cancer, PIK3CA is most frequently mutated, with mutations in AKT1, AKT2, and the proteins of the mTOR complex, except for RICTOR and mTOR, being relatively uncommon." (PMID 38473265, 2024).
cancer (continued). "Fascinatingly, ropivacaine was identified to directly bind to AKT1, although previous studies have reported that ropivacaine inactivated the PI3K/AKT signaling pathway in keratinocytes and cancer cells." (PMID 38523299, 2024). "The treatment of cancer cells with DBMSCs in the IC setting modulated the expression of various factors with a specific role in cellular adhesion, including AKT1, CALD1, CDH1, FN1, and STAT3." (PMID 39768220, 2024). "AKT1 is involved in various physiological processes of cancer cells, including cell proliferation, cell cycle control, apoptosis, cell metastasis, etc.." (PMID 38606171, 2024). "Elevated AKT1 expression has been observed in various cancer types, including GBM, during disease progression." (PMID 38360888, 2024). "In cancer cells with HER2 mutations, HER2 combines with STING and recruits the kinase AKT1 to phosphorylate TBK1, thus preventing the interaction between STING‐TBK1 and TBK1‐IRF3, ultimately shielding cancer cells from host antitumor immunity." (PMID 38525112, 2024). "Expanding this to more targets, for example AKT1, would potentially highlight this validated cancer target with compounds in clinical trials as a therapeutic target for MOC." (PMID 39184376, 2024). "Muhammad and colleagues tested the effectiveness of D. kaki polyphenols in inhibiting AKT1 (AKT Serine/Threonine Kinase 1) (6CCY)‐driven cancer growth." (PMID 39479648, 2024). "AKT1 can phosphorylate palladin’s Ser507, which controls the invasion and metastasis of cancer cells." (PMID 39062182, 2024). "The AKT1 oncogene is related to various cancers due to its critical role in the PIC3CA/AKT1 pathway; however, most of the studies screened the hotspot mutation AKT1 (E17K) with various incidences." (PMID 39329938, 2024). "Activation of Akt and Src signaling after radiotherapy has been frequently detected in cancer, and Akt1 is considered to be a key determinant of intrinsic resistance in several cancer types." (PMID 38473215, 2024). "AKT1 is involved in multiple signaling pathways that regulate cell survival, growth, and proliferation, and is considered an essential target for cancer therapy." (PMID 39162596, 2024). "Understanding the dynamics of intracellular signaling pathways, such as ERK1/2 (ERK) and Akt1/2 (Akt), in the context of cell fate decisions is important for advancing our knowledge of cellular processes and diseases, particularly cancer." (PMID 38834572, 2024). "PI3K is a downstream regulator of HER2 (human epidermal growth factor receptor 2) and other growth factors, and Akt1 promotes cancer progression and metastasis by regulating apoptosis-related genes and proteins." (PMID 38753638, 2024). "In the development and progression of cancer, AKT1, JUN, IL6, SRC, EGFR and BCL2 plays a critical role." (PMID 39011503, 2024). "The results, both in vitro and in vivo, showed that miR-409-3p’s ectopic expression blocked the migration and proliferation of cancer cells by specifically targeting AKT1." (PMID 38812786, 2024). "Somatic mutations have been identified in numerous genes, including PIK3CA, PTEN, Akt1 and other members of the PI3K-AKT-mTOR pathway, many of which have been clearly demonstrated to play important roles in promoting cancer cell proliferation and survival." (PMID 38616230, 2024). "In cancer cells, AKT1 is involved in proliferation and growth, promoting tumor initiation and suppressing apoptosis, whereas AKT2 regulates cytoskeleton dynamics, favoring invasion and metastasis." (PMID 39796647, 2024).
cancer (continued). "The protein AKT1 is an important objective for the treatment of cancer since its phosphorylation state is connected to decreased patient survival for malignancies other than EOC." (PMID 38836981, 2024). "Activation of the PI3K and AKT1 cascades in many types of human cancers, including GC, drives cancer cell growth and survival, leading to tumor invasiveness and drug resistance." (PMID 38283117, 2024). "Given that excessive activation of AKT1 is a prevalent factor in tumorigenesis, understanding the regulation of AKT1 is important to identify novel therapeutic targets in cancer." (PMID 38455765, 2024). "This is the most common mutation associated with AKT1, occurs in AKT2 and AKT3 at a much lower frequency in human cancers." (PMID 38336976, 2024). "The analysis of KEGG pathways also revealed that the putative antihepatic cancer targets identified (Akt1, EGFR, TNF, and ALB) are involved in multiple pathways associated with cancer development and progression." (PMID 39502516, 2024). "AKT1 is a key regulator of cell proliferation and drives cancer progression by transducing extracellular signals to the cytoplasm and nucleus through phosphorylation." (PMID 38837097, 2024). "The inhibition of the AKT1 gene leads to an increased chemosensitivity of cancer cells to cisplatin, and thus to the increase in its effectiveness." (PMID 39769428, 2024). "Activation of TGF-β signaling and phosphorylation of Smad2/3 can result in upregulation of circ-Akt1 which in turn increase Akt1 expression via miR-942-5p inhibition to then promote cancer metastasis and EMT induction." (PMID 38733529, 2024). "AKT1 plays a promotional role in epithelial-to-mesenchymal transition, invasion, disruption of tumor endothelial barrier, and cancer metastasis in cancer cells." (PMID 39022612, 2024). "The significance of AKT1 as a main target for addressing fatigue generated by cancer was demonstrated in a randomized controlled trial and an in vivo study." (PMID 38931288, 2024). "As a key protein in PI3K/AKT/mTOR signaling pathway, AKT1 can prevent apoptosis and promote cell survival, which is considered to be a major factor in many types of cancer." (PMID 39224778, 2024). "For instance, the PI3K–Akt signaling pathway, which includes the AKT1 gene, plays a pivotal role in cell proliferation and survival, often being deregulated in cancer." (PMID 39457716, 2024). "Carcinomas with apocrine differentiation exhibit a distinct set of somatic alterations, including mutations in PIK3CA, PIK3R1, and AKT1, indicating that activation of the PI3K pathway plays a crucial role in the molecular pathogenesis of the disease." (PMID 39272660, 2024). "We believe that using of PARPi monotherapy or in combination with radiation therapy is an appealing strategy for treating ARID1A-mutated cancers, as well as many other types of PI3K/Akt1-driven cancers." (PMID 36910637, 2023). "We propose that another appealing strategy for treating cancers with RAS mutations, as well as many other types of PI3K/Akt1-driven cancers, is the use of PARPi in monotherapy or in combination with chemo- or radiation therapy." (PMID 36910637, 2023). "PRMT5 has also been shown to directly methylate Akt1 arginine 15, a master regulator for cancer metastasis, leading to cancer cell invasion and migration." (PMID 37400960, 2023). "GAs that appeared after NACT were mainly involved in constitutive signaling by AKT1 E17K in cancer, neoplasm of the genitourinary tract, and VEGFR2‐mediated vascular permeability." (PMID 37356061, 2023). "It has been reported that JQ1 suppresses tumor growth through the regulation of the PI3K/AKT1/mTOR pathway in several cancer models, including GBM." (PMID 37108181, 2023).